STAT1 (signal transducer and activator of transcription 1)
Diseases named in the same sentence as STAT1 in open-access papers (continued):
Sharing a sentence is not in itself a finding about the gene and the disease.
Sepsis (61 papers, 2013 to 2026). Sepsis is defined as life-threatening organ dysfunction caused by a dysregulated host response to infection. "Other transcripts upregulated in CD5L− peritoneal cells, including Osm, Il18bp, Ripk1, Nub1, Tlr2, Stat1, Irf1, Nfkb1, Pik3r5, or their coding proteins, were already associated with sepsis severity." (PMID 38750020, 2024). "This is also consistent with additional experimental studies, reporting that STAT1 levels are upregulated in sepsis models; and that STAT1 deficient mice are protected from cecal-ligation and puncture-induced experimental sepsis." (PMID 34777396, 2021). "Furthermore, Stat1 deficiency inhibited the pyroptosis of macrophages and alleviated sepsis-induced multiple organ failure." (PMID 41078093, 2025). "Collectively, ginsenosides Rg1, Rb1, and Rk1 confer multi-faceted renoprotection against sepsis-induced acute kidney injury through multiple mechanisms, including TLR4, NF-κB, NLRP3, STAT1/3, and ferroptosis-associated pathways." (PMID 41415561, 2025). "In the validation set GSE209706, the sepsis (LPS-treated) group showed significantly increased levels of Cxcl10, Il6, and Stat1 compared to the control group." (PMID 40792069, 2025). "In the sepsis group, there was a notable increase in the expression of Cxcl10, Il6, and Stat1, which aligns with the findings from the RNA-seq data." (PMID 40792069, 2025). "Our study identified Stat1 as significantly upregulated in the sepsis group, which is consistent with its role in the immune response to sepsis." (PMID 40792069, 2025). "We additionally examined the effect of pharmacologically inhibiting STAT1 on cardiac dysfunction induced by sepsis." (PMID 40289345, 2025). "Cxcl10, Il6, and Stat1 showed higher levels of expression in the sepsis group than in the control group in the RNA-seq data (P < 0.05)." (PMID 40792069, 2025). "The MIR-574-5p has been shown to act on STAT1, decreasing its activity, and it is observed to be elevated in the serum of septic patients presenting decreased sepsis-induced AKI (acute kidney injury)." (PMID 39335561, 2024). "In both the S. aureus and E. coli baboon models after the induction of sepsis, we observed an upregulation of STAT1, similar to the upregulation observed for miR-93-5p." (PMID 37261908, 2023). "Sepsis is a condition that can result in multiple organ failure, leading to fatal outcomes, and the interaction of PD-1/PD-L1 with CD80, PI3K/Akt pathway, or STAT1 molecules plays an important role in the mechanism of sepsis-induced organ dysfunction." (PMID 38193090, 2023). "Ascorbic acid prevents sepsis-induced organ dysfunction through the p-STAT1/PD-L1 signaling pathway." (PMID 38193090, 2023). "Complement and/or CD14 inhibition successfully reduced the IFN-γ production in mice and baboons’ sepsis studies, thus preventing STAT1 and KLF4 overactivation." (PMID 36059503, 2022). "Recent studies have shown that the circadian clock regulates PKM2 expression and further controls the immune checkpoint PD-L1 in a STAT1-dependent manner in sepsis." (PMID 34862460, 2022). "In the experimental sepsis model, hyperactivation of STAT1 and STAT3 in the macrophages and monocytes induces immune system dysfunction and excessive release of inflammatory factors, resulting in sepsis-induced heart injury." (PMID 36619743, 2022). "Osteopontin is a biomarker of sepsis in humans and reportedly acts through Stat1 degradation to inhibit Nos2 transcription." (PMID 33849979, 2021). "Our data is consistent with a previous study demonstrating the role of STAT1 in sepsis pathogenesis." (PMID 32873853, 2020). "The promoter of the NOS2 gene, which is responsible for excessive NO production in sepsis in response to LPS, can be bound by several transcriptional factors, such as NF-κB, AP-1, and STAT-1." (PMID 29211014, 2017).
Sepsis (continued). "The hypocalcemia of critically ill patients with burn injury or sepsis is associated with CASR gene upregulation by TNF-alpha and IL-1beta via kappaB elements, and by IL-6 via Stat1/3 and Sp1/3 elements in the CASR gene promoters, respectively." (PMID 27679579, 2016). "Pharmacokinetic and mechanistic studies of IVC support plausible physiologic benefits through antioxidant effects, catecholamine biosynthesis, and immune modulation, with recent evidence showing down regulation of pro-inflammatory STAT1/PD-L1 pathways in experimental sepsis." (PMID 41815850, 2026). "Together, these results suggested that Mertk may regulate M1/M2 polarisation by tFNAs in sepsis‐induced intestinal injury and that the STAT1/SOCS signalling pathway may mediate this effect." (PMID 39844345, 2025). "(c) PHB2/STAT1/CCL2 axis modulation reverses IGFBP6-mediated sepsis pathology." (PMID 40892465, 2025). "Besides TLR4, several genes, including IFIH1 and STAT1, can affect M1 macrophage polarization and contribute to the progression of sepsis." (PMID 39294473, 2024). "STAT1, -5, and -6 are also important in the regulation of arginase activity, although this may be more pertinent for cancer than sepsis based on the subdued level of ARG1 expression in MDSCs identified from our septic patients." (PMID 38720891, 2024). "In this study, a PKM2/STAT1-mediated upregulation of PD-L1 on neutrophils and the anti-apoptotic effect of upregulated PD-L1 on neutrophils during sepsis were identified, which may result in increased pulmonary and hepatic neutrophil accumulation." (PMID 37131151, 2023). "Among these was also STAT1, a TF well known to play a regulatory role in sepsis." (PMID 37261908, 2023). "Our findings demonstrate that YTHDF2 plays an essential role as an inhibitor of inflammation by reducing the release of HMGB1 via inhibition of IL-6R/JAK2/STAT1 signalling, indicating that this pathway may be a novel therapeutic strategy for sepsis." (PMID 38026444, 2023). "Moreover, miR-30a was demonstrated to suppress IL-10-induced cytokine release via regulating STAT1-MD-2 in monocytes of sepsis." (PMID 33817242, 2020). "In an independent model of sepsis induced by cecal ligation and puncture, mice deficient in STAT1 were less susceptible to CLP-induced septic shock, indicating that STAT1 is critically involved in the development of systemic inflammation and the pathogenesis of sepsis." (PMID 32873853, 2020). "In sepsis, senescent red blood cells rupture and release heme and hemoglobin, which can induce ferroptosis in monocytes and macrophages, and may promote immunosuppression by interfering with signal transduction (such as the STAT1 pathway)." (PMID 41209006, 2025). "It has been shown that HDAC6 can activate STAT1 by promoting phosphorylation at Y701 of STAT1, which further increases interferon-regulatory factor-1 (IRF-1) expression, leading to increased iNOS levels in LPS-activated macrophages, thus promoting sepsis-associated ALI." (PMID 37175583, 2023). "However, it remains uncertain whether YTHDF2 affects HMGB1 release and whether the impact of YTHDF2 on HMGB1 release is connected to the regulation of the IL-6R/JAK2/STAT1 pathway in sepsis." (PMID 38026444, 2023). "The results showed that p‐STAT1, SOCS1 and SOCS3 expression levels decreased after sepsis‐induced intestinal injury compared to the control group." (PMID 39844345, 2025). "Ultimately, multiple signaling axes, including TLR4, IL-18, NADPH oxidase isoform 4 (NOX4), and the Janus kinase/signal transducer and activator of transcription-1/3 (JAK/STAT1/3) pathway, contribute to sepsis-induced acute kidney injury." (PMID 41415561, 2025). "Furthermore, In an animal model of sepsis-induced intestinal injury, naringenin treatment significantly suppressed M1 macrophage polarization and promoted M2 macrophage polarization by inhibiting the STAT1 signaling pathway, thereby alleviating sepsis-induced intestinal injury." (PMID 41375422, 2025).
Sepsis (continued). "Hence, we hypothesized that STAT1 could be a regulator of miR-93-5p in sepsis." (PMID 37261908, 2023). "Baicalin regulated multiple members of the STAT family, including STAT1, STAT3, STAT4, and STAT5, for treating T2D-induced liver tumor, sepsis, and myocardial ischemia reperfusion injury." (PMID 36324680, 2022). "Previously, we have utilized a SOCS-1 KIR blocking peptide termed iKIR that enhanced STAT-1 and STAT-3 phosphorylation in macrophages to promote cytokine storm during sepsis." (PMID 33690673, 2021). "We have previously shown that iKIR enhances both STAT-1 and STAT-3 in a murine model of sepsis and that iKIR-mediated STAT-3 activation amplifies HIF1α-mediated glycolysis." (PMID 33690673, 2021). "Together, our data provide an important initial clue that TICAM-2 mediated STAT1 activation via SFK is at least partially involved in the establishment of neutrophil exhaustion and sepsis severity." (PMID 32873853, 2020). "The prolonged exposure to IFN-γ, however, for example during chronic or acute inflammation, can increase STAT1 protein to WT levels such that the gain-of-function phenotype can come into effect and may manifest as disease exacerbation such as seen for LPS-induced murine sepsis." (PMID 27780205, 2016). "STAT1 knockout mice exhibited improved survival, attenuated systemic inflammation and diminished CXCL10 production during CLP-induced sepsis." (PMID 24890566, 2014). "Previous work in a mouse model of septicemia showed that naïve splenic CD4 T cells have a dampened response to IL-6 compared to uninfected mice, indicated by a reduced ability to phosphorylate STAT1 in response to ex vivo IL-6 stimulation." (PMID 23754944, 2013). "Stimuli related to sepsis (such as LPS) can down-regulate the expression of HLA-DR in monocytes, and the mechanism involves abnormal regulation of HLA-DR transcription (such as CIITA, IRF1) and signaling pathways (such as c-Src, Stat1 phosphorylation)." (PMID 41209006, 2025). "STAT1, a key transcription factor for TH1 and THαβ immunity, is downregulated in sepsis." (PMID 40699834, 2025). "Of note, LPS scarcely induced Stat1 and Tlr7 expression in Tyk2−/−cells, supporting the idea of a downregulated inflammation leading to the lack of sepsis described in Tyk2−/− mice in response to LPS." (PMID 38683377, 2024). "In summary, these findings demonstrate that YTHDF2 plays an essential role as an inhibitor of inflammation to reduce the release of HMGB1 by inhibiting the IL-6R/JAK2/STAT1 pathway, indicating that YTHDF2 is a novel target for therapeutic interventions in sepsis." (PMID 38026444, 2023). "Our results indicate that YTHDF2 plays an anti-inflammatory role by reducing the release of HMGB1 via inhibition of the IL-6R/JAK2/STAT1 pathway, demonstrating that targeting YTHDF2 may constitute a promising approach to sepsis treatment." (PMID 38026444, 2023). "Through the tests by western blot of STAT1 and STAT3, it revealed that the phosphorylation levels of STAT1 and STAT3 in the spleens of aged sepsis model rats were greatly increased at all time points compared with those in the spleens of normal rats, and maximal phosphorylation was observed at 24 h." (PMID 35197984, 2022). "STAT1 and SETD2 are also both over-expressed in late sepsis CD4+ T-lymphocytes." (PMID 34484194, 2021). "This led to enhanced STAT1–PD-L1 signalling in the absence of myeloid Bmal1 and an enhanced sepsis phenotype in a cecal ligation puncture model." (PMID 34858390, 2021). "Previous evidence had shown that mice lacking myeloid Bmal1 displayed heightened PKM2 mediated STAT1 phosphorylation in macrophages, which led to T cell exhaustion and an increase in sepsis and that PKM2 phosphorylates STAT1 to activate macrophages in a model of arthritis." (PMID 34858390, 2021).
Sepsis (continued). "TG-101348 (Fedratinib), a selective JAK2 inhibitor approved for myelofibrosis, has not yet been tested in sepsis but may exert therapeutic effects by modulating the JAK2/STAT1 signaling axis, a key regulator of inflammation and immune dysregulation in sepsis." (PMID 40792069, 2025).
gastric cancer (59 papers, 2007 to 2025). A primary or metastatic malignant neoplasm involving the stomach. "Based on these results, we propose that loss of PML protein expression in gastric cancer cells contributes to increased IP-10 transcription via enhancement of STAT-1 activity, which, in turn, promotes lymphocyte trafficking within tumor regions." (PMID 22022583, 2011). "We also previously reported a deficiency in STAT-1 component as a probable cause of resistance to IFNs detected in a gastric carcinoma cell line." (PMID 17319941, 2007). "Regarding the expression of JAK1/2, histone deacetylase (HDAC) has been shown to promote the activation of the IFN-γ/STAT1 pathway in gastric cancers, resulting in increased expression of PD-L1." (PMID 40909948, 2025). "Studies have elucidated a mutually antagonistic relationship between STAT1 and survivin in gastric cancers." (PMID 40909948, 2025). "Compared with nearby normal tissues, TRIM21 expression was reduced in gastric cancer, which was mediated by STAT1." (PMID 39768197, 2024). "MTMR2 promotes invasion and metastasis of gastric cancer via inactivating IFNγ/STAT1 signaling and modulates TIME by promoting the progression of NK/T cell lymphoma by targeting JAK1." (PMID 39408697, 2024). "The invasion and metastasis of gastric cancer can be promoted upon inactivation of IFNgamma/STAT1 signaling." (PMID 36593458, 2023). "ADAR (an interferon-inducible RNA-editing enzyme) mitigates IFN signaling in gastric carcinoma through down-regulating STAT1 and IRF9 by miR-302a." (PMID 37408777, 2023). "LSECtin expressed in lymph nodes in nude mice affected the expression of circFBXL4, miR-146a-5p and STAT1 in GC cells, suggesting that LSECtin further promotes the development of gastric cancer by regulating the circFBXL4/miR-146a-5p/STAT1 axis." (PMID 35821222, 2022). "Adenosine deaminase acting on RNA (ADAR1) was reported to block the transport of ISGF3 into the nucleus by upregulating miRNA-302a and thereby targeting IRF9 and STAT1 in gastric cancer." (PMID 36104718, 2022). "MTMR2 an essential promoter in gastric cancer invasion and metastasis by inactivating IFNA1/STAT1 signalling and acts as a new prognostic indicator and a potential therapeutic target for gastric cancer." (PMID 35057823, 2022). "STAT1 was selected for correlation analysis in 10 gastric cancer and 5 normal gastric mucosa in-house clinical samples due to its highest r value." (PMID 32615958, 2020). "In a previous study, we suggested that OPN protected gastric epithelial cells and cancer cells from inducible nitric oxide synthase-mediated apoptosis through STAT1 downregulation, thereby promoting the development and progression of gastric cancer." (PMID 27888617, 2016). "The results showed that the density of CD8+ T cells, CD20+ B cells, and CD33+/p-STAT1+ cells in tumors was a useful criterion for the prediction of survival in advanced gastric cancer patients." (PMID 23307253, 2013). "This study examined the relationship between the survival rate of gastric cancer and the density of immune cells, including TILs and CD33+/p-STAT1+ cells, which represented MDSCs, to evaluate the role of the immune response in gastric cancer progression." (PMID 23307253, 2013). "For this reason, CD33+/p-STAT1+ cells are defined as a specific type of MDSC in gastric cancer tissues, although further functional analysis is required." (PMID 23307253, 2013). "Overall, this study demonstrated that the density of CD33+/p-STAT1+ cells is an independent prognostic factor for patients with stage IIIa gastric cancer, indicating that CD33+/p-STAT1+ cells play a central role in the local immune response in gastric cancer." (PMID 23307253, 2013). "Using SNU-638 gastric cancer cells, we also found that STAT-1 DNA binding of Pml siRNA-transfected SNU-638 cells was enhanced compared to that of control siRNA-transfected cells, after treatment with IFN-γ (compare lanes 3 and 5)." (PMID 22022583, 2011).
gastric cancer (continued). "Besides, a study on gastric cancers has revealed that HOXC9 contributes to tumor progression by inhibiting STAT1 signaling." (PMID 40909948, 2025). "H. pylori can active the expression of STAT1 and PD-L1 which may prevent immune surveillance in the gastric mucosa, allowing premalignant lesions to progress to gastric cancer." (PMID 37363723, 2023). "In addition, dihydroartemisinin ameliorated multiple sclerosis and gastric cancer through regulating STAT1 signaling." (PMID 36324680, 2022). "H. pylori-induced activation of STAT1 and PD-L1 expression may prevent immune surveillance in the gastric mucosa, allowing premalignant lesions to progress to gastric cancer." (PMID 35456965, 2022). "The activation of Stat1 upregulates the expression of PD-L1 and PD-L2 in gastric cancer." (PMID 36525420, 2022). "As the cancers progress, studies have shown that the upregulation of PD-L1 was due to the activation of the Janus kinase 2/signal transducers and activators of the transcription 1 (JAK2/STAT1) signalling pathway in EC and other cancers such as colorectal, pancreatic, and gastric cancer." (PMID 36010904, 2022). "To explore the role of gastric epithelial cells and immune cells in the activation of STAT1 and the induction of PD-L1 expression, we first infected gastric cancer cell lines NUGC4 and NCI-N87 with the H. pylori G27 strain and detected p-STAT1 and PD-L1 expression by western blot." (PMID 35456965, 2022). "Hence, our results suggest that ADAR1 regulates IFN signaling in gastric cancer through the suppression of STAT1 and IRF9 via miR-302a, which is independent from the RNA editing of known IFN production pathway." (PMID 32867271, 2020). "This study examined the relationship between gastric cancer survival and the density of immune cells, including CD8+ T cells, CD20+ B cells, and CD33+/p-STAT1+ cells, which represent myeloid-derived suppressor cells, to evaluate the role of immune cells in the progression of gastric cancer." (PMID 23307253, 2013). "The IFITM family may also be mutated in gastric cancer, regulating the entry of viruses into host cells, activating IFI6 and FKBP10 and leading to TF phosphorylation like STAT1." (PMID 39228892, 2024). "In addition, CCR1 and STAT1 are protective factors for gastric cancer." (PMID 35174205, 2022). "Therefore, CD33+/p-STAT1+ cells were proposed to be a subset of MDSCs in gastric cancer tissues." (PMID 23307253, 2013). "SOCS1 has been identified as a critical inhibitor of gastric cancers, liver cancers, and other gastrointestinal malignancies by blocking the IFN-γ/STAT1 pathway." (PMID 40909948, 2025). "Turning to the stability and nuclear translocation of STAT1, PML, a recognized tumor suppressor protein, is reduced in advanced gastric cancers but further contributes to creating an immune-enhanced tumor microenvironment." (PMID 40909948, 2025). "Research highlights that GBP5 is markedly upregulated in gastric cancer, which is mediated by the IFN-γ/STAT1 signaling." (PMID 40909948, 2025). "In gastric cancer cells, expression of the YARS protein is impaired by the STAT1 inhibitor fludarabine." (PMID 40597232, 2025). "In gastric cancer cell models, the knockdown of HDAC3 inhibited the nuclear translocation of STAT1, impaired IFN-γ signaling, and reduced B7-H1 expression in HGC-27 cells." (PMID 40006729, 2025). "STAT1 (Signal transducer and activator of transcription 1) represses the transcriptional activity of TRIM21 in gastric cancer." (PMID 40936722, 2025). "The distributions of SNVs from the TCGA-STAD cohort showed that altered frequencies of STAT1 and IFIT3 came first and third among 48 gastric cancer patients." (PMID 36311733, 2022). "In the case of stomach cancer cells, it appears that DUOX2 upregulation at the mRNA and protein levels by NF-kB and Stat-1 is sufficient to bypass the tolerance levels." (PMID 34439340, 2021).